TXNDC2 (thioredoxin domain containing 2)
Description:
Probably plays a regulatory role in sperm development. May participate in regulation of fibrous sheath (FS) assembly by supporting the formation of disulfide bonds during sperm tail morphogenesis. May also be required to rectify incorrect disulfide pairing and generate suitable pairs between the FS constituents. Can reduce disulfide bonds in vitro in the presence of NADP and thioredoxin reductase.
Synonyms: SPTRX; SPTRX1
Tractability: No criterion of Open Targets' tractability assessment is met for any kind of drug.
Gene: Protein-coding gene on chromosome 18 (9,885,766 to 9,889,275, forward strand). Ensembl gene ENSG00000168454.
Subcellular location: Cytoplasm
Gene Ontology:
Molecular function: protein binding; thioredoxin-disulfide reductase (NADPH) activity
Biological process: cell redox homeostasis; spermatogenesis; cellular oxidant detoxification
Cellular component: cytoplasm
Genetic constraint (gnomAD): Loss-of-function variants: 4 observed, 3.2 expected, observed/expected ratio (o/e) 1.25, 90% interval 0.57 to 1.9. That is too few expected variants to judge how well the gene tolerates losing a copy. Missense variants: 509 observed, 579.24 expected, observed/expected ratio (o/e) 0.88, 90% interval 0.82 to 0.95. Synonymous variants: 183 observed, 219.04 expected, observed/expected ratio (o/e) 0.84, 90% interval 0.74 to 0.94.
Homologues: Orthologues: chimpanzee TXNDC2 (88% identical), macaque TXNDC2 (46% identical), mouse Txndc2 (41% identical), rat Txndc2 (39% identical), dog TXNDC2 (38% identical), Drosophila melanogaster CG14221 (9% identical). Paralogues in human: TXN (13% identical), TXNDC8 (9% identical), TXNL1 (9% identical), TXN2 (7% identical).
Diseases named in the same sentence as TXNDC2 in open-access papers:
TXNDC2 is named in the same sentence as 13 diseases in open-access papers, as found by Europe PMC text mining. Sharing a sentence is not in itself a finding about the gene and the disease. The quoted sentences say what the papers report.
Azoospermia (2 papers, 2021 to 2023). Absence of any measurable level of sperm,whereby spermatozoa cannot be observed even after centrifugation of the semen pellet. "The association of PRM1/2 with male azoospermia is well-documented, but the relationship between TXNDC2 deficiency and the azoospermia phenotype, sperm retrieval, and pathology has not been elucidated." (PMID 34158577, 2021). "Therefore, the aim of this study was to evaluate the expression levels of TXNDC2 concomitantly with protamination genes in different azoospermia pathologies." (PMID 34158577, 2021). "Moreover, TXNDC2 was correlated with phenotypes of severe azoospermia pathology (SH and SCOS)." (PMID 34158577, 2021). "TXNDC2 (effect size = − 4.25, FDR = 1.44E−15), PRM1 (effect size = − 5.37, FDR = 1.99E−10), PRM2 (effect size = − 5.16, FDR = 3.60E−10), and TNP1 (effect size = − 7.05, FDR = 6.48E−16) were all downregulated in the idiopathic azoospermia dataset." (PMID 34158577, 2021). "TXNDC2, along with protamine 1 and 2 (PRM1 and PRM2), was significantly decreased in patients with different patterns of NOA compared to OA patients, suggesting that TXNDC2, PRM1, and PRM2 have a robust power to predict sperm retrieval and are correlated with phenotypes of severe azoospermia." (PMID 37174638, 2023).
diffuse large B-cell lymphoma (1 paper, 2023). "For example, the expressions of TXNDC2, TXNDC3, and TXNDC6 have a significance in both testicular and systemic diffuse large B-cell lymphoma." (PMID 37686174, 2023).
glioma (1 paper, 2025). A benign or malignant brain and spinal cord tumor that arises from glial cells (astrocytes, oligodendrocytes, ependymal cells). "For example, the redox-associated genes NCF2, VASN, FKBP1B, and TXNDC2 have been identified as central genes, potentially serving as a dependable prognostic indicator for the clinical management of glioma." (PMID 41049606, 2025).
lymphoma (1 paper, 2021). A malignant (clonal) proliferation of B- lymphocytes or T- lymphocytes which involves the lymph nodes, bone marrow and/or extranodal sites. "TXNDC2 was detected both in the cytoplasm and the nucleus of normal testis tissue samples and weakly in the nucleus of lymphoma samples." (PMID 33603952, 2021). "Western blotting, from whole cell lysates of the cell lines representing systemic lymphomas, shows that TXNDC2 can be expressed in systemic DLBCL (Western blot)." (PMID 33603952, 2021). "Overall, the expression of TXNDC2 and TXNDC3 was weaker in lymphoma tissue compared to seminiferous tubule cells, whereas the expression level of TXNDC6 was deemed low in all the sample types." (PMID 33603952, 2021). "The score of the cytoplasmic and nuclear TXNDC2 in normal seminiferous tubule cells was significantly higher than that in systemic and testicular lymphoma (p < 0.005, dot blots), but the expression did not vary significantly between the lymphoma groups (dot blots)." (PMID 33603952, 2021).
cancer (2 papers, 2013 to 2020). A tumor composed of atypical neoplastic, often pleomorphic cells that invade other tissues. "Down regulation of TXNDC2, an antioxidant enzyme is directly related to cisplatin resistance in many cancer cells." (PMID 33680914, 2020). "This indicates that GPX5 and TXNDC2 are both good candidates to mediate the upregulation of ROS observed upon p38 MAPK inhibition in cancer cells." (PMID 24115572, 2013). "We have also identified two antioxidant genes, GPX5 and TXNDC2, which are positively regulated by p38 MAPK signalling in cancer cells and control the basal JNK activity levels." (PMID 24115572, 2013).
TXNDC2 also shares sentences with these, for which no sentence is quoted: Alzheimer disease (1 paper); atherosclerosis (1); Autoimmunity (1); oligospermia (1); Parkinson disease (1); schizophrenia (1); Sertoli Cell-Only Syndrome (1); thyroid disease (1).